KRT6A (keratin 6A)
Diseases named in the same sentence as KRT6A in open-access papers (continued):
Sharing a sentence is not in itself a finding about the gene and the disease.
tumor (continued). "To further confirm the prognosis of these findings, we performed co‐staining for pan‐cytokeratin, ASCL1, and KRT6A on clinical tumour samples from treatment‐naïve KRASG12C‐mutant LUAD, confirming the presence of two distinct subpopulations within individual tumours." (PMID 41025426, 2025). "In summary, KRT6A plays a promoting role in the transformation of LUAD to squamous type, and the promoting effect of LSD1 on KRT6A may directly affect the malignant progression of the tumor." (PMID 40568576, 2025). "There are also studies suggesting that KRT6A may be the origin of a tyrosine highly correlated with tumor occurrence and development." (PMID 38656878, 2024). "Moreover, ST treatment remarkably reduced KI67 and KRT6A expression in tumor tissues compared with DMSO treatment." (PMID 37647260, 2023). "Importantly, we confirmed the negative correlation of the spatial TNOD marker MPPED1 and the spatial TINF marker KRT6A expression at the tumor-stroma interface by RNA FISH." (PMID 35986012, 2022). "Furthermore, immunohistochemical staining results showed significantly increased levels of KRT6A protein in tumor tissues than normal adjacent tissues (p < 0.05)." (PMID 34235156, 2021). "(F) Expression of the luminal markers, FOXA1 (1.8-fold increase) and GATA3 (1.8-fold increase), and the basal markers, CDH3 (6-fold decrease) and KRT6A (9-fold decrease) in tumor xenografts from mice treated with 5’-azacitidine compared to those of the vehicle control." (PMID 31036156, 2019). "The previous finding that tumor heterotransplants generated from Cd2+- and As3+-transformed UROtsa cells had increased squamous differentiation also correlates with the enhanced expression of keratin 6a." (PMID 18414623, 2008). "This highlighted the limit of RNA‐based selection as some genes such as KRT6A were linked to the epithelial component, regardless of the subtype, but appeared as strongly differential due to the tumor cellularity of basal‐like tumors being much higher than classical tumors." (PMID 39935174, 2025). "Thus, evidence suggests that overexpression of keratin 6a could be a biomarker for tumor progression and that it might also participate in the enhanced urothelial cell accumulation of the environmental pollutant arsenic." (PMID 18414623, 2008). "Mechanistically, KRT6A promotes tumor progression through the pentose phosphate pathway regulated by MYC, and LSD1 can promote KRT6A gene expression." (PMID 40568576, 2025). "We also excluded five markers that showed expression in both tumor subtypes (AGR2, SNAI2, KRT6A, MET, SLC16A3)." (PMID 39935174, 2025). "Pairwise analysis revealed that tumor tissues exhibited significantly elevated expression of KRT81, KRT6A, KRT17, and KRT14, which were positively correlated with FSTL3 expression, compared to that in normal tissues." (PMID 38240936, 2024). "One study revealed that silencing KRT6A led to a reduction in the expression of TIM-2 and MMP-9, two proteins involved in tumor invasion and metastasis in nasopharyngeal carcinoma." (PMID 39194725, 2024). "qRT-PCR and IHC showed increased ANLN, RHOV, and KRT6A expression in the LUAD cells and tumor tissues." (PMID 37974107, 2023). "Several well-known tumor markers for HNSCC were highly expressed in almost every cell cluster, including Keratin 6A (KRT6A), Keratin 14 (KRT14), and Cadherin-1 (CDH1)." (PMID 36982384, 2023). "For the univariate cox analysis of early prognostic genes (FAM83A, KRT6A, and CYP4B1) related to OS, DSS, DFI, and PFI of 32 tumors, we selected the top one to three with the lowest p-value in the analysis of tumor prognosis." (PMID 37081097, 2023). "Among the five RMScore genes, four (ANLN, KRT6A, PITX3, and NTSR1) were identified to be upregulated, while CYP17A1 was identified to be downregulated in TCGA-LUAD tumor tissues compared with paired normal tissues." (PMID 35859664, 2022).
tumor (continued). "Additionally, it is not immediately clear whether KRT6A c.745T>C mutation could lead to an increased expression of the protein and a resultant alteration of the tumor phenotype." (PMID 35884495, 2022). "To verify the carcinogenic roles of SRXN1 and KRT6A in NSCLC, we measured the expression of these genes in 75 paired NSCLC and non-tumor tissues by RT-qPCR." (PMID 35071014, 2021). "The gene expression results showed that the expression levels of MS4A1 and KRT6A in tumour tissues were higher than in normal tissues, while CRTAC1 expression in tumour tissues was lower than in normal tissues." (PMID 34060213, 2021). "Next, correlation analysis indicated that expression of c-MYC and KRT6A, LSD1, G6PD were positively correlated in NSCLC tumor tissues." (PMID 34235156, 2021). "The results showed that the expression levels of MS4A1 and KRT6A in tumour tissues were higher than in normal tissues, while CRTAC1 expression in tumour tissues was lower than in normal tissues." (PMID 34060213, 2021). "The tumor growth curves indicated significant growth inhibition in the si-SRXN1-1 and si-KRT6A-1 groups (both P < 0.05), compared with the NC and control groups, respectively." (PMID 35071014, 2021). "mRNA expression of the two basal-type markers KRT6A and KRT14 as well as EGFR confirmed comparable levels between the original tumor tissue and p-SCC." (PMID 32978523, 2020). "Among the top downregulated ones we found keratin 6A and keratin 20 (KRT6A and KRT20) suggestive of the reduction of tumor cells as the result of TCB-mediated killing." (PMID 33330050, 2020). "FABP5, IVL, KRT6A, KRT15, KRT16, and TIMP2 expression profiles suggested relatively significant elevated expression in tumor tissues compared with the corresponding normal tissues." (PMID 32934956, 2020). "The muscle invasive tumour, however, showed a basal subtype (higher expression of CDH3, CD44, KRT5 and KRT6A) and likewise high aggressiveness (higher expression of KPNA2, BIRC5, CDC25B, COL4A1, and MSN)." (PMID 28916750, 2017). "Regarding the expression of luminal and basal biomarkers, Layer3.1 tumor presented higher expression of KRT20, a luminal-papillary biomarker, whereas Layer3.2 had higher expression of KRT5, KRT6a, KRT14, and CD44 basal biomarkers, but also PGM5, DES, and SGCD luminal-infiltrated biomarkers." (PMID 41516353, 2026). "In the group of smokers, compared to non-smokers, KRT6A protein concentration was higher in the tumor (0.02126 (0.01055–0.03044) vs. 0.00858 (0.00669–0.01089)); (p = 0.0061)." (PMID 39000463, 2024). "Due to the role of KRT6 proteins in cell growth, invasion, and migration processes, it is hypothesized that the levels of KRT6A, KRT6B, and KRT6C will be changed in tumor samples compared to margin samples in patients with HNSCC." (PMID 39000463, 2024). "Through assay for transposase-accessible chromatin using sequencing (ATAC-seq), we detected increased chromatin openness of squamous markers (TP63, KRT5, KRT6A and KRT14) and reduced chromatin accessibility of adenomatous markers (KRT7 and MLPH) in the DR tumor cells." (PMID 39687207, 2024). "In order to identify the key regulators in the ICD risk subgroups, first we verified the mRNA expression levels of these eight genes, and we found that only SFTPB and SERPIND1 were highly expressed in normal tissues, whereas FAM83A, FDCSP, KRT6A, RHOV and TPX2 were highly expressed in tumor tissues." (PMID 39247599, 2024). "Finally, through RT-PCR and WB, we found that the expression levels of tumor cells (A549, H1975, and A549) in BESA-2B cells were significantly higher than those in FAM83A and KRT6A, while CYP4B1 was the opposite." (PMID 37081097, 2023). "Similarly, in the analysis of the CPTAC dataset in the UALCAN database, the protein expression levels of KRT6A and FAM83A were higher in the tumor group, while CYP4B1 was the opposite." (PMID 37081097, 2023).
tumor (continued). "UBE2S, HMMR, TMPRSS11E and KRT6A were found to be up-regulated in tumor tissues relative to surrounding non-cancerous and normal tissues in the screening cohort." (PMID 37199651, 2023). "Furthermore, ST inhibited the CRC cell proliferation in vivo, and reduced KRT6A and KI67 expression in xenograft tumor." (PMID 37647260, 2023). "In addition, epithelial cell differentiation regulation-related genes, such as AKR1B1, SPRR1B, and keratin genes KRT6A, KRT19, and KRT17 were also highly expressed in mixed-lineage tumor cells." (PMID 35962452, 2022). "Interestingly, although OS is a tumor of mesenchymal origin, upregulated genes in MG-OKS cells included epithelial-related genes, such as small proline-rich protein 2A (SPRR2A), SPRR1A, keratin 6A (KRT6A), and keratin 6B (KRT6B)." (PMID 33008481, 2020). "Notably, though, all overexpressed keratins, i.e. KRT5A, KRT6A, KRT7, KRT14, KRT17, were found to play a role as LUAD tumor progression determinants." (PMID 30473748, 2018). "Notably, all overexpressed keratins, i.e. KRT5A, KRT6A, KRT7, KRT14, KRT17, were found to play a role as LUAD tumor progression determinants." (PMID 30473748, 2018). "However, neither SRXN1 nor KRT6A expression was correlated significantly with age, sex or tumor size (P > 0.05)." (PMID 35071014, 2021). "Genes up-regulated in cells from tumor specimens grown under CRC culture conditions are enriched with markers for lung basal cells such as TP63 (> 60 fold), podoplanin (PDPN, > 36 fold), cytokeratin genes KRT6A (> 729 fold), KRT6B (> 98 fold), and adhesion molecules LGALS7B (> 200 fold)." (PMID 28052041, 2017). "An archival specimen that contained within a single tissue block both a profile of a high-grade urothelial cancer and adjacent normal (noncancerous) urothelium showed that the high-grade tumor was immunoreactive for keratin 6a, whereas the normal urothelium showed no staining for keratin 6a." (PMID 18414623, 2008). "However, keratin 6a staining was focal, and all four tumors showed some areas of negative-staining tumor cells." (PMID 18414623, 2008). "Compared to that of the paired normal tissues, the mRNA expression levels of KRT6A and KRT6B, but not that of KRT6C, were significantly increased in the paired tumor tissues." (PMID 38398015, 2024). "Tumor samples with absent immunoexpression of GATA3, FOXA1 and CK5/6 showed significantly lower transcript levels of GATA3, FOXA1 and KRT5/KRT6A, respectively (p < 0.001, p = 0.0130, p < 0.0001 and p = 0.0278)." (PMID 32758253, 2020).
cancer (53 papers, 2008 to 2026). A tumor composed of atypical neoplastic, often pleomorphic cells that invade other tissues. "Reportedly, KRT6A is associated with cell proliferation and invasion, which drives cancer progression by upregulating glucose-6-phosphate dehydrogenase (G6PD) through MYC signaling pathway." (PMID 36505456, 2022). "A receiver operating characteristic (ROC) curve analysis indicated the high diagnostic value of SRXN1 and KRT6A for smoking and cancer." (PMID 35071014, 2021). "Finally, a comprehensive pan-cancer analysis in TCGA cohort was performed to conduct the expression and mutational landscape of HMMR, FAM83A, and KRT6A, aiming to understand their roles across diverse cancer types." (PMID 38740918, 2024). "Overall, systematic elucidation of the structure-function-pathway-clinical axis of KRT6A offers new opportunities for precision medicine and supports its potential as a therapeutic target in cancer management." (PMID 41648000, 2026). "Overexpression of KRT6A and KRT17 has been linked to hyperproliferation and the progression of various cancers, prompting extensive research into the mechanisms regulating their expression." (PMID 41439999, 2025). "KRT6A, a type II keratin involved in the epidermalization of squamous epithelium, plays a critical role in cell migration and cancer metastasis." (PMID 38740918, 2024). "Most importantly, we discovered that Ep_VGLL1 was spatially correlated with both classical (Ep_TRIM54) and basal-like cancer (Ep_KRT6A) clusters." (PMID 38297291, 2024). "Some studies found upregulated KRT6A levels in other types of the cancer sample, compared to matched normal samples." (PMID 39000463, 2024). "KRT81, KRT6A, and KRT13 are examples of these genes that have been linked to cancer metastasis and migration in humans." (PMID 37817112, 2023). "The KRT6A protein is a type II cytokeratin, and the KRT6A gene is highly expressed in different types of cancer." (PMID 34060213, 2021). "In both control and cancer organoids, the expression of Hopx and the suprabasal keratinocyte markers Krt13, Krt4, and Krt6a increased with pseudotime while Lgr6-expressing cells were enriched in undifferentiated cells." (PMID 34785704, 2021). "Second, it remains unclear whether clinical variables, such as age, sex, or cancer stage, affect KRT6A and KRT17 expression in human MG and MGC, which should be evaluated in a larger cohort." (PMID 41439999, 2025). "Similarly, S100A2, KRT14, KRT17, and KRT6A were overwhelmingly expressed in cancer cells and their expression values were significantly higher than the other cells (log10FC > 3 and P < 0.001)." (PMID 34326696, 2021). "The KRT6A-positive subset of mammary epithelial cells can be induced to form cancer by ErbB2." (PMID 33221741, 2020). "Two other specimens of high-grade cancer, one that had invaded the underlying muscle layer and one that had not, were also shown to stain for keratin 6a." (PMID 18414623, 2008). "Additionally, it has been suggested that keratin 6A may play a role in promoting the transformation of cancer stem cells (CXCR4high/CD133high) and the epithelial–mesenchymal transition (EMT)." (PMID 38612418, 2024). "Analysis through OncodriveCLUST disclosed that KRT6A replaces JAK2V617F as the more prominent disease driver in MPN–SC, whereas a major mutation in this gene (KRT6A c.745T>C) in our patients is linked to human carcinoma and predicted to be pathogenic in COSMIC database." (PMID 35884495, 2022). "TM4SF1 positive cancer cell subpopulation (TPCS) was characterized by the upregulation of TM4SF1, ITGA6, and KRT6A." (PMID 38582099, 2024). "Using these eight cancer types, we defined a set of 76 core basal genes, which include the classic markers KRT5, KRT6A/B/C, and DSG3." (PMID 38791964, 2024). "Among them, three genes, i.e., KRT6A, KRT13, and KRT81, were related to cancer metastasis and migration." (PMID 37817112, 2023).
cancer (continued). "Among them, five genes (FGG, MYH15, STARD4, SYTL4, and TMEM267) were first associated with cancer procession, while the other three (KRT81, KRT6A, and KRT13) have previously been confirmed to be related to cancer metastasis and migration." (PMID 37817112, 2023). "In contrast, ginsenoside Rg1 downregulated the mRNA expression of ARG2, MMP1, S100A4, and RAPSN, and upregulated the mRNA expression of LAMC2, DSC2, KRT6A, and FOSB, thereby enhancing the anti-cancer function of granulocytes inhibited by NA." (PMID 36817446, 2023). "The heat map shows positive correlation between GJB2 and the five genes (GJB6, KRT6A, KRT6B, KRT14, and IVL) in pan-cancer." (PMID 37427102, 2023). "Previous studies indicated that KRT6A and its downstream gene S100A2 were the biomarkers and therapeutic targets for various cancers, including CRC." (PMID 37647260, 2023). "We found that the cancer subtype markers (GRP, CHGB, NEUROD1, and CHGA for NET; KRT5, DSC3, KRT6B, TP63, and KRT6A for SCC; and NKX2-1, KRT7, NAPSA, and MUC1 for ADC) were specifically expressed in the corresponding cancer subtypes." (PMID 35962452, 2022). "KRT6A was reported to promote NSCLC cell growth and invasion through the MYC-regulated pentose phosphate pathway and to promote EMT and cancer stem cell transformation in LUAD." (PMID 36185621, 2022). "Intriguingly, we found that none of the major cancer cell subclusters (Ep_TRIM54, Ep_VGLL1, and Ep_KRT6A) exhibited preferences for Fb_LRRC15." (PMID 38297291, 2024). "KRT6A was highly expressed in cystitis and low-grade carcinoma cells, and was not present in high-grade carcinoma tissues." (PMID 35330118, 2022). "Mechanistically, KRT6A overexpression is sufficient to upregulate glucose-6-phosphate dehydrogenase (G6PD) levels and increase the pentose phosphate pathway flux, an essential metabolic pathway to support cancer cell growth and invasion." (PMID 34235156, 2021). "Such classification is achieved based on genomic and transcriptomic analyses, which point to differential expression of specific markers among tumors: the basal cytokeratins KRT5/KRT6A and KRT14, as hallmarks of basal BlCa, and the luminal markers FOXA1 and GATA3, as hallmarks of luminal cancer." (PMID 32758253, 2020). "The roles of DCBLD2, E2F7, and KRT6A have not been explored in PDAC but these proteins are known to have context dependent effects in various cancers." (PMID 30092011, 2018). "PyMT is a viral oncoprotein that activates Src and PI3K, and is apparently sufficient in transforming mammary cells to cancer, when its gene is either expressed as a transgene or delivered by RCAS into the mammary epithelium of MMTV-tva or keratin 6a-tva transgenic lines." (PMID 24265712, 2013). "In addition, the authors reported that KRT6A overexpression can affect the upregulation of G6PD (glucose-6-phosphate dehydrogenase), resulting in activation of the metabolic pathway promoting invasion and the growth of cancer cells." (PMID 39000463, 2024). "The first is that keratin 6a expression might be only a biomarker of upstream events in cancer development and progression and have no direct influence on either of these processes." (PMID 18414623, 2008). "Thus, under this hypothesis, keratin 6a would be a biomarker for an activated cell proliferation pathway and need not have a direct role in cancer development or progression." (PMID 18414623, 2008). "Not surprisingly, similarity among different cancer types was identified in only 6 out of 23 clusters, including E3 (IRS2, KRT6A), E5 (CD24, STMN1), E8 (GKN1, MUC5AC), E9 (PHGR1, TFF3), E10 (TFF3, TPO) and E13 (VTN and ITIH5)." (PMID 36333338, 2022).
infection (9 papers, 2015 to 2025). The state of being infected such as from the introduction of a foreign agent such as serum, vaccine, antigenic substance or organism. "Previously, we reported that bactericidal fragments of keratin 6A (KAMPs) have neutral or modest positive charge and are expressed in stratified epithelial cells, suggesting a novel, direct antimicrobial function for keratins in epithelial innate defense against infection." (PMID 27891122, 2016). "The spatial tropism exhibited in the histopathology is supported by the levels of Krt6a seen in DTV-infected tissues, which exhibit anti-microbial properties in the olfactory bulb, an area with extensive DTV infection." (PMID 38932113, 2024). "Furthermore, proteins related to the cytoskeleton and cytoskeleton remodeling (KRT2 and PLXNA4) and genes coding for components of the cytoskeleton, KRT13 (LOC100515166), KRT17 (LOC100737113), KRT6A, and BFSP1, were significantly higher expressed after infection with swH1N1 compared to huH1N1." (PMID 39247193, 2024). "Although there is a lack of direct evidence that correlates with TAMs, KRT6A has been found to play a role in producing AMPs for innate immune defense against infection, which may indirectly affect macrophages." (PMID 33221741, 2020). "We have reported transgenic mice expressing tva from the promoter of MMTV (MMTV-tva) for indiscriminate infection of the luminal epithelium, and from the promoters of WAP, TOP, and Krt6a for selective infection of WAP+, canonical Wnt signaling-active, and Krt6a+ cells, respectively." (PMID 25635772, 2015).